CD14 (CD14 molecule)
Diseases named in the same sentence as CD14 in open-access papers (continued):
Sharing a sentence is not in itself a finding about the gene and the disease.
heart failure (13 papers, 2014 to 2024). Inability of the heart to pump blood at an adequate rate to meet tissue metabolic requirements. "At the same time, an increased content of intermediate CD14++CD16+ monocytes was associated with a better prognosis in patients with heart failure." (PMID 34206012, 2021). "CD14 was associated with both renal dysfunction and the combined renal dysfunction and heart failure in all EV sub‐fractions, and with presence of heart failure in the high density lipoprotein sub‐fraction." (PMID 32648717, 2020). "In the HDL fraction, CD14 was associated with an OR of 1.57 [95% confidence interval (95% CI): 1.16–2.13] for heart failure, OR of 1.87 (95% CI: 1.18–2.96) for renal dysfunction, and OR of 2.78 (95% CI: 1.78–4.32) for the combination of both conditions." (PMID 32648717, 2020). "EV levels of CD14 and Cystatin C are associated with both renal dysfunction and heart failure in patients presenting with dyspnoea at the emergency department." (PMID 32648717, 2020). "Previously, we reported that EV protein levels of Cystatin C, CD14, SerpinG1, and SerpinF2 were associated with heart failure in dyspnoeic patients." (PMID 32648717, 2020). "The primary aim of this study is to investigate the association between the selected EV proteins (Cystatin C, CD14, SerpinG1, and SerpinF2) with both renal dysfunction and heart failure in patients with acute dyspnoea." (PMID 32648717, 2020). "We provide the first data showing that Cystatin C and CD14 in circulating EVs are associated with both renal dysfunction and heart failure in patients presenting with acute dyspnoea." (PMID 32648717, 2020). "Higher CD14 levels were also associated with increased risk of heart failure in the HDL and in TEX sub‐fraction." (PMID 32648717, 2020). "CD14 was also associated with increased risk of renal dysfunction and the combination of renal dysfunction and heart failure in LDL and TEX sub‐fraction." (PMID 32648717, 2020). "In this cross‐sectional cohort study, we showed that EV levels of CD14 and Cystatin C are associated with both renal dysfunction and heart failure in patients presenting with dyspnoea." (PMID 32648717, 2020). "Extracellular vesicle levels of CD14, SerpinG1 and SerpinF2 are associated with the occurrence of heart failure in subjects suspected for acute heart failure, suggesting common underlying pathophysiological mechanisms for heart failure and vascular events." (PMID 26820481, 2016). "Similar associations between CystatinC (OR 2.01, p = 0.02), CD14 (OR 1.30, p = 0.2) and SerpinG1 (OR 1.43, p = 0.04) and heart failure were found." (PMID 26820481, 2016). "Circulating CD14 EVs may then increase inflammatory processes in the blood vessels and heart, resulting in higher risk of heart failure." (PMID 32648717, 2020). "In addition to CD14, we found that Cystatin C both in EVs and in plasma was associated with both renal dysfunction and heart failure." (PMID 32648717, 2020). "Similarly, we found an increased risk of both heart failure and renal dysfunction in patients with higher EV CD14 levels." (PMID 32648717, 2020). "This suggests that CD14 in EVs may reflect toll‐like receptor involvement in both heart failure and renal dysfunction, although the exact underlying mechanisms of this finding remain unclear." (PMID 32648717, 2020). "In this, our multinomial model showed the highest OR for patients with both heart failure and renal dysfunction, indicating that elevated EV CD14 levels associate with higher risk of the concurrence of both conditions than with either heart failure or renal dysfunction in isolation." (PMID 32648717, 2020). "Seven genes highly expressed in treatment-responsive CD14+ monocytes can be used for subtyping analysis of heart failure patients." (PMID 38517374, 2024).
heart failure (continued). "Univariant analysis showed significance for age, serum albumin, heart failure and P. Adjusted model analysis, kept significance for age, serum albumin, P and the percentage of proinflammatory monocytes CD14+/CD16+." (PMID 34300056, 2021). "In the current study, vesicle levels of pro‐inflammatory CD14 were elevated in patients with heart failure, renal dysfunction, and the combination of both conditions." (PMID 32648717, 2020). "Median levels of Cystatin C and CD14 were the highest in patients with both heart failure and renal dysfunction in all three EV sub‐fractions." (PMID 32648717, 2020). "Identifying common markers for heart failure and renal dysfunction, such as EV CD14 and Cystatin C, is of interest because of the multifactorial feedback pathways linking the heart and kidneys." (PMID 32648717, 2020). "Extracellular vesicles co-precipitating with LDL (LDL-EVs) exhibited higher levels of CystatinC (OR 1.84, p-value <0.001) and of CD14 (OR 1.26, p = 0.03) in heart failure-patients." (PMID 26820481, 2016). "By contrast, reduced levels of the classical CD14++CD16− monocyte subset are reported in heart failure, compatible with remodelling roles for different subsets." (PMID 25061264, 2014). "Systemic inflammation driven by exposure to endotoxin in patients with heart failure results in downregulation of monocyte CD14+ expression and increased soluble CD14 through shedding of this receptor from the cellular membrane." (PMID 25061264, 2014). "Furthermore, this study mainly focused on the changes and therapeutic responses of CD14+ monocytes, while stem cell therapy for heart failure involves complex cell interactions." (PMID 38517374, 2024). "Furthermore, extracellular vesicle CD14- and SerpinF2-levels were significantly higher in heart failure patients with preserved ejection fraction than in those with reduced ejection fraction." (PMID 26820481, 2016). "Downregulation of CD14+ is consistent with the hypothesis that chronic systemic exposure to low plasma levels of endotoxin occurs as a result of (occult) cardiac failure." (PMID 25061264, 2014). "The expression of therapy-related CD14+ monocytes in these groups was significantly different, which suggests that the activation of AP-1 family and the therapy-related CD14+ monocytes may help identify and screen heart failure patients suitable for the MSCs therapy." (PMID 38517374, 2024). "There are few and relatively recently published studies that have found elevated CD14++CD16+ monocyte counts in patients with both acute and stable chronic heart failure as well as an association of these proinflammatory monocytes with heart failure severity and decreased GFR levels." (PMID 37189647, 2023). "However, this study is the first indication that EV levels of CD14 and Cystatin C may be common markers for heart failure and renal dysfunction." (PMID 32648717, 2020). "Patients who suffered a heart failure during AMI (n = 17) had increased levels of platelet (CD61+)-and monocyte (CD14+)-derived cMPs carrying TF (CD142+) (P<0.0001 and 0.004, respectively)." (PMID 28207887, 2017). "In addition, classical (CD14++CD16-) and inflammatory (CD14++CD16+) monocytes are positively correlated with IL-6 production, described as a biomarker of cardiac failure and severity in CCC patients." (PMID 36839443, 2023). "Although we cannot discriminate between soluble and membrane CD14 in our immunoassay, our data suggest that EV‐bound membrane CD14 and not the soluble plasma CD14 is important in heart failure and kidney dysfunction." (PMID 32648717, 2020). "After adjustment for confounders, levels of TEX SerpinG1 (aOR 1.55, p = 0.004) and SerpinF2 (aOR 0.71, p = 0.021) remained statistically significantly related to heart failure, whereas CD14 and CystatinC TEX-levels did not." (PMID 26820481, 2016).
heart failure (continued). "We reasoned that monocyte CD14 surface expression would be reduced in patients with low AT, compared to age-matched controls with no clinical evidence for cardiac failure." (PMID 25061264, 2014). "With regard to the etiology of heart failure, we found increased levels of CD16-positive monocytes, that is, both CD14++CD16+ and CD14+CD16++ monocytes in patients with nonatherosclerotic CVD." (PMID 37189647, 2023).
liver cirrhosis (13 papers, 2010 to 2025). "Induction of CD14 + Trem-1 + iNOS + intestinal macrophages in liver cirrhosis patients released IL-6, NO, and accelerated intestinal permeability." (PMID 37273916, 2023). "As expected, the percentage of TEMs in peripheral blood monocytes of HCC patients was significantly increased compared with that in patients with HBV-related liver cirrhosis and healthy donors according to their surface marker (CD14, CD16 and Tie2)." (PMID 26599011, 2015). "In patients with liver cirrhosis, both increased peripheral CD14+CD16− and CD14+CD16+ monocytes have been reported from small clinical studies." (PMID 20548789, 2010). "Given the marked preferential intrahepatic accumulation of CD14+CD16+ monocytes in liver cirrhosis, we next aimed to define the likely function of this subset in the pathogenesis of chronic liver inflammation and fibrosis." (PMID 20548789, 2010). "CD14+CD16+ intermediate monocytes were shown to contribute to liver cirrhosis in adults." (PMID 40607400, 2025). "In patients with liver cirrhosis, intrahepatic monocytes/macrophages are significantly increased, and our analysis revealed that this can be mainly attributed to a selective accumulation of CD14+CD16+ monocytes/macrophages in the cirrhotic liver." (PMID 20548789, 2010). "In a flow cytometry analysis of VDR expression on PBMCs in patients with liver cirrhosis, hepatitis C virus positive patients, and healthy controls, median fluorescence intensity was higher for VDR expression on CD14+ cells compared to CD3+ cells." (PMID 39409006, 2024). "The levels of CD3+VDR+ and CD14+VDR+ cells were significantly increased in HCV+ patients and patients with liver cirrhosis compared with healthy controls." (PMID 37511164, 2023). "When compared to healthy controls, only 7 DEGs, including 6 up-DEGs (TYMP, TYROBP, TGFBI, LILRA2, GNLY, and GZMB) and 1 down-DEG (CD14) were common to CHB, liver cirrhosis, and HCC." (PMID 35265561, 2022). "Soluble CD14, IL-18 and other immune activation mediators are produced in abundance in the liver in response to HCV and can act to perpetuate intrahepatic inflammation and progression of fibrosis and cirrhosis of the liver." (PMID 35482664, 2022). "Plasma DKK1 level and the percentage of TEMs in peripheral CD14+CD16+ monocytes from HCC patients (n = 82), HBV-related liver cirrhosis (LC) patients (n = 29), chronic hepatitis B (CHB) infected patients (n = 28) and healthy volunteers (n = 31) were analyzed by ELISA and flow cytometry." (PMID 28902891, 2017). "Our data demonstrate the expansion of CD14+CD16+ monocytes in the circulation and liver of CLD-patients upon disease progression and suggest their functional contribution to the perpetuation of intrahepatic inflammation and profibrogenic HSC activation in liver cirrhosis." (PMID 20548789, 2010).
metabolic syndrome (13 papers, 2012 to 2025). A cluster of metabolic risk factors for CARDIOVASCULAR DISEASES and TYPE 2 DIABETES MELLITUS. "CD14 was significantly related to T2D, metabolic syndrome, glucose, and the Atherogenic Index of Plasma (AIP)." (PMID 35846887, 2022). "In contrast, the percentage of NCM expressing CD16 and low CD14 levels exhibited a significant 65% increase in the metabolic syndrome group as compared to controls (13.47 ± 1.59 versus 8.12 ± 0.89, resp)." (PMID 29850624, 2018). "Additionally, we observed a significant effect of metabolic syndrome MetS on the increase of exosomal Cystatin C and CD14." (PMID 35846887, 2022). "The aim of this study was to analyze the effect of T2D, metabolic syndrome, and the atherogenic index of plasma on the levels of cystatin C, CD26, and CD14 proteins in serum exosomes." (PMID 35846887, 2022). "The results demonstrated that age, dyslipidemia, atrial fibrillation, triglyceride, MR (grades 2 to 4), mean TLR2+/CD14+ cells, TLR2+/CD14+ cells <25%, TLR4+/CD14+ cells <0.25%, mean MPO+/CD14+cells, MPO+CD14+ cells <20%, sST2 <14,000 (pg/mL), and mean sST2 were significantly predictive of mild CCS." (PMID 32054047, 2020).
psoriatic arthritis (13 papers, 2010 to 2025). Joint inflammation associated with psoriasis. "On the other hands, in bone disease patients, CD16 could be a potential marker of OC precursors: in psoriatic arthritis a higher percentage of circulating CD14+ CD16+ cells associated with a higher bone erosion has been reported." (PMID 26376614, 2015). "We aimed to investigate differential gene expression in peripheral CD14+ monocytes between patients with psoriatic arthritis (n = 15) and healthy controls (HCs; n = 15)." (PMID 38672131, 2024). "Our previous study demonstrated that higher expression of miR-146a-5p in CD14+ monocytes of psoriatic arthritis than that in HCs." (PMID 32560314, 2020). "CD14+CD16+ monocytes also appear expanded in many diseases characterized by bone derangement, such as Gaucher disease or psoriatic arthritis." (PMID 36497460, 2022).
Autoimmunity (12 papers, 2013 to 2024). The occurrence of an immune reaction against the organism's own cells or tissues. "CD14+ associated pathways noted to be affected were those associated with angiogenesis, blood vessel development, autoimmunity, cell movement and migration." (PMID 25333715, 2014). "Its expression is profound in circulating CD14+ monocytes which was reported to be increased in various autoimmune conditions." (PMID 39050398, 2024). "This study shows that the CDC42-related MetSig identifies the antigen-presenting CD14+ cells that migrate to joints to coordinate autoimmunity." (PMID 37662900, 2023). "Our findings suggest that autoimmunity in DAIH is promoted by CD14++ monocytes predominantly through activation of inflammatory signaling pathways." (PMID 30072988, 2018). "TLR2 and TLR4 silencing in CD14++ monocytes of these patients prevents Treg differentiation to Th1-like Tregs and thus IFN-γ secretion by Tregs of these patients, suggesting that autoimmunity is promoted by CD14++ monocytes predominantly through activation of inflammatory signaling pathways." (PMID 30072988, 2018). "Here, we show that GM-CSF and IL-3, hematopoietic cytokines that play a central role in regulating myeloid cell expansion and effector response in several in vivo models of inflammation and autoimmunity, modulate human CD14+ monocyte response in short- and long-term models of trained immunity." (PMID 28138327, 2016). "Our data advocates for a scenario in which the worsening of autoimmunity in MyD88–/–Aire–/– mice could be caused by the lack of MyD88 signaling in mTECshigh, downregulation of their chemokines needed to recruit CD14+moDCs and, consequently, suboptimal production of thymic Tregs." (PMID 32398640, 2020). "That study further showed that the frequency of the CD14++CD16+ monocyte subpopulation in RA promoted a proinflammatory cytokine milieu that induced the generation and maintenance of Th17 cells, which are deeply involved in the pathogenesis of autoimmunity." (PMID 31169830, 2019).
co-infection (12 papers, 2014 to 2025). "Of the co-infected individuals, CD14 genetic variants ranged from 18.8% vs 21.5%, 33.3% vs 44.4%, 9.7% vs 11.8% for single versus schistosome co-infection for the wild type (CC), heterozygous (CT) and mutant (TT) variants respectively." (PMID 37684680, 2023). "Among PWH, HCV coinfection is associated with significant elevations in the monocyte activation markers soluble CD14 and IL-6, suggesting that HCV independently contributes to intestinal barrier damage." (PMID 31304190, 2019). "Taken together, it is possible that additional factors—such as chronic elevation of LPS or co-infection—may alter the association of the CD14 −260 SNP with CVD." (PMID 27495090, 2016). "Coinfection was accompanied by an increase in the proportions of CD14+CD16+ pro-inflammatory subsets of monocytes and release of pro-inflammatory cytokines in the plasma." (PMID 31133721, 2019). "Additionally, markers of innate immune activation such as soluble CD14 predict poor host response to interferon-alpha-based HCV therapy during HIV-HCV coinfection." (PMID 24809719, 2014). "The elevation in levels of plasma inflammation and microbial translocation biomarkers, especially soluble CD14 and interleukin-6 in people with HIV/HCV coinfection compared to PWH, have also been previously observed." (PMID 40006998, 2025). "Monocyte surface CD163 expression was quantified by flow cytometry, and found to be significantly elevated on the total CD14+ monocyte population among CTN-055 participants regardless of HCV co-infection, as compared to PLWH ref. at both W0 (Adj." (PMID 35371104, 2022). "In the present study, we characterized the role of CD14+CD16+ monocytes in HIV-NCI in the context of viral suppression with a standard ART backbone (tenofovir-emtricitabine), while minimizing effects of confounders by excluding individuals with active substance use and HCV coinfection." (PMID 39253970, 2024).
gram-negative bacterial infections (12 papers, 2006 to 2025). Infections caused by bacteria that show up as pink (negative) when treated by the gram-staining method. "As supporting evidence, immune-compromised mice (Lbp −/− and CD14 −/−) succumbed to fatality caused by gram-negative bacterial infection, despite a delayed response 4 h after the bacterial invasion." (PMID 25102863, 2014). "CD14 deficient mice show decreased inflammatory responses to lipopolysaccharide induced cardiac damage, and show decreased lethality in response to certain gram-negative bacterial infections." (PMID 30485272, 2018). "In vivo trials with CD14 knock out mice have shown a protective effect of CD14 by attenuating bacterial growth and dampening the systemic inflammatory response against Gram-negative bacterial infection." (PMID 35429403, 2022). "Increased serum CD14 levels have been shown to correlate with shock and greater mortality in patients with gram-positive and gram-negative bacterial infections." (PMID 28122493, 2017). "CD14 is involved in LPS recognition and mediates the activation of monocytes/macrophages in gram-negative bacterial infection." (PMID 28122493, 2017). "A remarkable feature of TLR2 and TLR4 is their ability to cooperate with CD14 on the host cell surface in sensing LPS of Gram negative bacterial infection." (PMID 23492674, 2011). "For Gram-negative bacterial infections, the CD14 molecule confers LPS sensitivity to neutrophils, which is necessary to initiate host immune responses." (PMID 18691417, 2008). "In other models of Gram-negative bacterial infection, CD14 gene knockout mice had been proved to have altered outcomes of infection." (PMID 16995947, 2006). "Lbp is involved in the acute phase immunologic response to Gram-negative bacterial infections through binding to bacterial lipopolysaccharide (LPS), thereby eliciting immune responses by presenting the LPS to the cell surface pattern recognition receptors CD14 and Tlr4." (PMID 24063402, 2013).